MALAT1 (metastasis associated lung adenocarcinoma transcript 1)
Diseases named in the same sentence as MALAT1 in open-access papers (continued):
Sharing a sentence is not in itself a finding about the gene and the disease.
Sepsis (65 papers, 2017 to 2025). Sepsis is defined as life-threatening organ dysfunction caused by a dysregulated host response to infection. "MALAT1 is associated with promoting inflammatory responses by facilitating NF-κB nuclear translocation, exacerbating lung injury during sepsis." (PMID 40135054, 2025). "Another pro-inflammatory lncRNA, MALAT1 (metastasis-associated lung adenocarcinoma transcript 1), contributes to endothelial dysfunction in sepsis." (PMID 40868190, 2025). "In lethal models of sepsis, polymorphonuclear-MDSCs (PMN-MDSCs) decrease in early but increase and become activated in late sepsis, which is contrary to the expression of metastasis-associated lung adenocarcinoma transcript 1 (Malat1)." (PMID 38385073, 2024). "TEM images revealed that sepsis‐induced mitochondrial shrinking and mitochondrial crest reduction in the kidney tissues were abolished by MALAT1 deficiency." (PMID 39390627, 2024). "In this study, to further explore MDSC development, we profiled the expression of mRNA and non-coding RNA in BMCs and identified differential metastasis-associated lung adenocarcinoma transcript 1 (Malat1) expression during the early and late stages of sepsis." (PMID 38385073, 2024). "Increasing evidence suggests that LncRNAs can be used as potential diagnostic and prognostic biomarkers of ARDS in sepsis, such as MALAT1 and PVT1." (PMID 38238652, 2024). "MSC-derived exosome delivered miR-26a-5p mediated MALAT1 breakdown and consequently protected sepsis-associated ALI." (PMID 37398640, 2023). "MALAT1 deficiency dramatically inhibits oxidative stress, and thus attenuates liver injury in sepsis." (PMID 37398640, 2023). "To identify the role of MALAT1 and miR-26a-5p in sepsis-associated ALI, we subjected WT or Malat1-deficient mice with CLP in the presence or absence of miR-26a-5p." (PMID 37398640, 2023). "In the present study, we discovered a novel role of MSCs and MSC-derived exosome for treating ALI in sepsis, and revealed the underlying mechanism that exosome-delivered miR-26a-5p attenuate the syndrome by silencing MALAT1." (PMID 37398640, 2023). "To investigate the mechanism of MALAT1 involving sepsis-associated ALI, we determined MDA and GSH levels in the liver of mice." (PMID 37398640, 2023). "MALAT1 was reported to cause sepsis-mediated organic injuries by promoting apoptosis and enhancing immune response both in vivo and in vitro." (PMID 34630395, 2021). "The miR-150-5p/NF-κB axis is another axis that mediates the effects of MALAT1 in sepsis-associated cardiac inflammation." (PMID 34956235, 2021). "Recent evidence assigned immunoregulatory functions to the MALAT1 lncRNA, as results showed that a deficiency in MALAT1 resulted in cytokine dysregulation and immune-mediated diseases, such as sepsis and atherosclerosis." (PMID 34638541, 2021). "LncRNA such as NEAT1, HOTAIR, and MALAT1 have been identified as being significantly associated with the development of sepsis." (PMID 34870560, 2021). "Expression of MALAT1 was found to be an independent risk factor for sepsis, poor prognosis and septic shock." (PMID 34956235, 2021). "LncRNA MALAT1 was correlated with good prediction of sepsis and risk of 28-day death with an AUC of 0.823 and 0.755, respectively." (PMID 34630395, 2021). "(a) We detected the value of lnc‐MALAT1/miR‐125a axis in predicting 28‐day mortality risk, while the correlation of lnc‐MALAT1/miR‐125a with long‐term clinical outcomes in sepsis patients needed further exploration." (PMID 32309886, 2020). "And in sepsis patients, lnc‐MALAT1 relative expression was negatively associated with miR‐125a relative expression." (PMID 32309886, 2020). "The aim of the current study was intended to investigate the underlying role of lncRNA MALAT1 in the progression of sepsis." (PMID 31830649, 2020).
Sepsis (continued). "The present study aimed to investigate the potential value of long non‐coding RNA metastasis‐associated lung adenocarcinoma transcript 1 (lnc‐MALAT1)/microRNA (miR)‐125a axis in disease management and prognosis surveillance of sepsis." (PMID 32309886, 2020). "In sepsis patients, lnc‐MALAT1/miR‐125a axis was positively associated with APACHE II score (r = .549, P < .001) and SOFA score (r = .507, P < .001)." (PMID 32309886, 2020). "(b) In sepsis patients, lnc‐MALAT1/miR‐125a axis was positively associated with general disease severity, organ injury, and inflammation level." (PMID 32309886, 2020). "This study aimed to investigate the plasma long noncoding RNA metastasis‐associated lung adenocarcinoma transcript 1 (lncRNA MALAT1) expression with risk, severity, inflammation level, and prognosis in sepsis." (PMID 31301104, 2019). "Cardiomyocytes transfected with MALAT1 siRNA were less susceptible to LPS-induced cell apoptosis, suggesting that MALAT1 induction is a mechanism of cardiomyocyte apoptosis or injury in response to sepsis." (PMID 29662883, 2018). "Since both BMCs and PMN-MDSCs have low Malat1 expression during late sepsis, we questioned whether there is a causal relationship between decreased Malat1 expression and PMN-MDSC expansion." (PMID 38385073, 2024). "The cause of this discrepancy in the role of macrophage MALAT1 in sepsis development is currently unknown, and more research on this subject will aid in reaching a definitive conclusion." (PMID 37509544, 2023). "Replenishment of miR‐26a‐5p protected against hepatocyte death and liver injury caused by sepsis through targeting Metastasis Associated Lung Adenocarcinoma Transcript 1 (MALAT1), a long non-coding RNA highly presented in hepatocyte and liver under sepsis and inhibiting anti-oxidant system." (PMID 37398640, 2023). "LncRNA metastasis-associated lung adenocarcinoma transcript 1 (MALAT1) has been linked to sepsis." (PMID 35741168, 2022). "The relative expression of lnc‐MALAT1 and miR‐125a in all participants was detected by reverse transcription quantitative polymerase chain reaction, and the inflammatory cytokines in plasma of sepsis patients were measured by enzyme‐linked immunosorbent assay." (PMID 32309886, 2020). "Recent evidence has documented the regulatory role of long non-coding RNA (lncRNA) metastasis-associated lung adenocarcinoma transcript 1 (MALAT1) during the inflammatory process, the effects of which in the development of sepsis have become the focus of the current study." (PMID 31830649, 2020). "Lnc‐MALAT1/miR‐125a axis presents excellent value in differentiating sepsis patients from healthy controls and also exhibits positive association with general disease severity, organ injury, inflammation level, and mortality in sepsis patients." (PMID 32309886, 2020). "Nonetheless, the diagnostic and prognostic role of lncRNA MALAT1 in sepsis patients remains largely unknown." (PMID 31301104, 2019). "Thus, the aim of this study was to investigate the plasma lncRNA MALAT1 expression with risk, severity, inflammation level, and prognosis in sepsis." (PMID 31301104, 2019). "Thus, MALAT1 is the target of miR-26a-5p in the treatment of sepsis-associated ALI." (PMID 37398640, 2023). "MALAT1 depletion is responsible for the sepsis inflammatory response by inhibiting the expressions of IL-6 and TNF-α and the NF-κB signaling pathway by upregulating miR-150-5p." (PMID 40041174, 2025). "In resveratrol-treated sepsis model rats, the expression of MALAT1 was downregulated, the secretion of inflammatory factors in serum was reduced, and renal function was improved." (PMID 40657645, 2025). "By sequestering miR-150-5p, MALAT1 upregulates intercellular adhesion molecule 1 (ICAM-1) expression, worsening pulmonary inflammation in sepsis-associated ALI." (PMID 40868190, 2025). "Studies have shown that MSCs-exo alleviates sepsis-related acute liver injury by inhibiting MALAT1 through miR-26a-5p35." (PMID 38734709, 2024).
Sepsis (continued). "Animal studies show that MALAT1 expression surges with sepsis induction; reducing MALAT1 lessens inflammation and mortality, possibly by suppressing M1 and enhancing M2 macrophage polarization." (PMID 38473915, 2024). "Collectively, these data suggest that the sepsis-induced decrease in Malat1 expression promotes the expansion and immunosuppression of PMN-MDSCs by enhancing STAT3 phosphorylation." (PMID 38385073, 2024). "Downregulation of MALAT1 restrained sepsis‐induced ferroptosis in renal cells by recruiting the RNA binding protein FUS to reduce the stability of acyl‐CoA synthetase family member 2 (ACSF2) mRNA." (PMID 39390627, 2024). "In the present study, we found that Malat1 was continuously low expressed in BMCs during late sepsis, and Malat1 knockdown promoted the expansion and immunosuppressive function of PMN-MDSCs." (PMID 38385073, 2024). "Malat1 inhibitor appeared to impair bacteria clearance, resulting in more severe bacteremia and higher mortality in late sepsis." (PMID 38385073, 2024). "Malat1 is a lncRNA that affects immune responses during sepsis and is related to the phenotypes of immune cells such as macrophages 26,27." (PMID 38385073, 2024). "Genetic knockdown of MALAT1 protected mouse kidney and HK‐2 cells against sepsis via repressing ferroptosis." (PMID 39390627, 2024). "For example, alterations in the levels of lncRNA HOTAIR and MALAT1 in sepsis patients were investigated." (PMID 39735547, 2024). "RNA-seq data showed that LncRNA Malat1 expression was elevated in early sepsis and decreased in late sepsis, compared to that in BMCs under physiological conditions, which was contrary to the change in the ratio of PMN-MDSCs among BMCs." (PMID 38385073, 2024). "Although some studies have shown elevated Malat1 expression in septic patients and animal/cell models 26,46, few have concluded that Malat1 is decreased in sepsis." (PMID 38385073, 2024). "In conclusion, our data provide novel mechanistic information regarding Malat1 regulation of PMN-MDSCs in sepsis." (PMID 38385073, 2024). "Our data showed that persistent low Malat1 expression in late sepsis promotes the expansion and activation of PMN-MDSCs by maintaining the phosphorylation of STAT3." (PMID 38385073, 2024). "For instance, suppressing MALAT1 with siRNA mitigates sepsis-related inflammation, while its overexpression exacerbates atherosclerosis severity." (PMID 38473915, 2024). "An increase in lncRNA MALAT1 levels was detected in the serum of late-onset sepsis patients and in activated primary macrophages and macrophage cell lines." (PMID 37509544, 2023). "A recent study reported that MALAT1 was downregulated in patientswith sepsis and LPS-induced RAW264.7 murine macrophages, while hsa-miR-346 wasupregulated." (PMID 39077015, 2023). "A recent study reported that MALAT1 inhibits anti-oxidant system and thus promotes sepsis in CLP model." (PMID 37398640, 2023). "Depletion of MALAT1 significantly inhibited sepsis-induced mice death by improving the anti-oxidant capacity of glutathione." (PMID 37398640, 2023). "MALAT1 also mediates proinflammatory changes, further implicating MALAT1 as an attractive therapeutic target of sepsis." (PMID 37509544, 2023). "Another study suggested that MALAT1 depletion is responsible for the sepsis inflammatory response by inhibiting the expression of IL-6 and TNF-α and the NF-κB signaling pathway by upregulating miR-150-5p." (PMID 37109540, 2023). "Other lncRNAs, such as lncRNA DLX6 antisense RNA 1, MALAT1, PVT1, and GAS5, are involved in pyroptosis in sepsis-associated renal injury." (PMID 36299256, 2022). "They found that miR-150-5p is inhibited by MALAT1 and, therefore, they play opposing roles in sepsis-induced myocardial inflammation." (PMID 36012630, 2022). "Resveratrol downregulated miR-205 expression, suggesting that the inhibition of the lncRNA MALAT1/miR-205 axis by this flavonoid protects against sepsis-induced AKI." (PMID 35912113, 2022).
Sepsis (continued). "Resveratrol rescues the viability and cytokine release of LPS-treated HK2 cells by inactivating the lncRNA MALAT1/miR-205 axis and attenuates sepsis-induced AKI." (PMID 36299256, 2022). "RT-qPCR analyses showed that MALAT1 was upregulated, while CRNDE was downregulated in sepsis and overexpression of MALAT1 and CRNDE downregulated the expression of each other." (PMID 35300579, 2022). "Several studies suggested the potential of other lncRNAs, such as NEAT1 and MALAT1, as biomarker for sepsis." (PMID 34055659, 2021). "Significantly, Cheng and his colleagues recently found five lncRNAs (FENDRR, MALAT1, TUG1, CRNDE, and ANCR) were correlated with sepsis-associated mRNA modules perhaps by acting as competing endogenous RNAs (ceRNAs)." (PMID 34483898, 2021). "MALAT1 is another lncRNA that affects immune responses of rats with LPS-induced sepsis through influencing the miR-146a/NF-κB P65 axis." (PMID 34956235, 2021). "Chen and colleagues demonstrated that metastasis-associated lung adenocarcinoma transcript 1 (MALAT1) promoted cardiac inflammation and dysfunction in sepsis through targeting microRNA (miRNA)-125b and regulating the p38 NF-κB pathway." (PMID 33869780, 2021). "Previous studies have also found that lncRNA HOTAIR, NEAT1, and MALAT1 were differentially expressed in sepsis patients." (PMID 34514170, 2021). "Most notably, MALAT1/miR-125a axis has been shown to discriminate sepsis patients based on their severity of diseases, organ damage, levels of inflammatory responses and mortality." (PMID 34956235, 2021). "The lnc-MALAT1/miR-125a axis presents excellent value in differentiating sepsis patients from healthy controls using peripheral blood samples." (PMID 34041287, 2021). "In one previous study, five lncRNAs, including FENDRR, MALAT1, TUG1, CRNDE, and ANCR, were associated with sepsis." (PMID 34483898, 2021). "The expression level of MALAT1 was significantly increased in sepsis in vitro, and MALAT1 knockout also reduced serum levels of cTn-I, TNF-α, IL-1β, IL-6, IL-10, IL-17, IFN-γ, C5, and C5a." (PMID 34514170, 2021). "Excessive inflammatory response can exacerbate sepsis-induced heart dysfunction; several studies have shown lncRNA MALAT1 involvement via regulation of inflammatory response." (PMID 34055659, 2021). "Downregulation of MALAT1 attenuated the burn injury and post-burn sepsis-induced inflammatory reaction." (PMID 34956235, 2021). "A prospective cohort study of 120 sepsis patients showed that lnc-MALAT1 accurately diagnosed sepsis (AUC 0.910) and predicted 28-day survival (AUC 0.886) better than the APACHE II score (AUC 0.868) and lactate levels (AUC 0.868)." (PMID 33803628, 2021). "MALAT1 was found to aggravate the sepsis-induced cardiac inflammation via regulating the miR-150-5p/NF-κB signal pathway." (PMID 34126975, 2021). "To validate the effect of lncRNA MALAT1 on sepsis in vivo, we silenced lncRNA MALAT1 in septic mice." (PMID 31830649, 2020). "Collectively, all of the evidence illustrated that lncRNA MALAT1 functioned through recruiting EZH2 in skeletal muscle cells in sepsis." (PMID 31830649, 2020). "High expression of lncRNA MALAT1 along with low expression of breast cancer susceptibility gene 1 (BRCA1) were identified in septic mice and human skeletal muscle cells of sepsis." (PMID 31830649, 2020). "According to the median level of lnc‐MALAT1/miR‐125a axis, lnc‐MALAT1, or miR‐125a, all sepsis patients were divided into those with high level and low level, respectively." (PMID 32309886, 2020). "For instance, a recent study reported that MALAT1 knockdown markedly reduced lung injury induced by sepsis." (PMID 33134293, 2020). "Lnc‐MALAT1/miR‐125a axis was increased in sepsis patients (9.713 [4.217‐22.037]) compared with healthy controls (0.905 [0.566‐1.852]) (P < .001)." (PMID 32309886, 2020).
Sepsis (continued). "In the present study, we found that (a) lnc‐MALAT1/miR‐125a axis was upregulated in sepsis patients compared with healthy controls and presented with excellent value in distinguishing sepsis patients from healthy controls." (PMID 32309886, 2020). "They found that miR-150-5p is inhibited by MALAT1 and therefore they have opposite roles in the sepsis-induced myocardial inflammation." (PMID 33396834, 2020). "Meanwhile lnc‐MALAT1 (AUC: 0.866, 95% CI: 0.830‐0.901) and miR‐125a (AUC: 0.892, 95% CI: 0.860‐0.924) exhibited good value in discriminating sepsis patients from healthy controls as well." (PMID 32309886, 2020). "It has also been reported that lncRNA MALAT1 can regulate sepsis-induced cardiac inflammation and dysfunction." (PMID 31830649, 2020). "Lnc‐MALAT1/miR‐125a axis was increased in sepsis patients compared with healthy controls (P < .001) and was of excellent value in distinguishing septic patients from healthy controls with the area under the curve (AUC) of 0.931 (95% CI: 0.908‐0.954)." (PMID 32309886, 2020). "Following that, we further detected the association of lnc‐MALAT1/miR‐125a axis with APACHE II score, SOFA score, biochemical indexes, and inflammatory cytokines in sepsis patients." (PMID 32309886, 2020). "In the present study, we found that lnc‐MALAT1/miR‐125a axis was upregulated in sepsis patients compared with healthy controls and presented with excellent value in distinguishing sepsis patients from healthy controls." (PMID 32309886, 2020). "Plasma lncRNA MALAT1 expression was elevated in sepsis patients than HCs (P < 0.001), and ROC curve disclosed that it had a good value in predicting sepsis risk with an area under curve (AUC) of 0.823 (95% CI: 0.783‐0.864)." (PMID 31301104, 2019). "Plasma lncRNA MALAT1 expression was elevated in sepsis patients than that in HCs (P < 0.001), and ROC curve analysis disclosed that lncRNA MALAT1 expression had a good value in predicting sepsis risk with an AUC of 0.823 (95%CI: 0.783‐0.864)." (PMID 31301104, 2019). "Blood samples within 24 hours after admission of sepsis patients and those on enrollment of HCs were collected, and then, plasma was separated for lncRNA MALAT1 and miR‐125b expressions detections by RT‐qPCR." (PMID 31301104, 2019). "RIP and qRT-PCR analysis revealed that the lncRNAs HULC, UCA1, and MALAT-1 were significantly enriched with the CMPs after sepsis." (PMID 31231228, 2019). "It is highly possible that there are other targets whose expression is also modulated following induction in expression of the HULC, UCA1, and MALAT-1 lncRNAs during sepsis in endothelial cells." (PMID 31231228, 2019). "In a recent study, MALAT1 expression was increased by LPS stimulation in murine cardiomyocytes and in cardiac tissue of a mouse sepsis model." (PMID 29662883, 2018). "Additionally, MALAT1 silencing exerts cardioprotective effects on sepsis-induced myocardial injury by reducing inflammation and apoptosis of cardiomyocytes through miR-26a-5p/Rcan2 axis." (PMID 41170388, 2025). "In late-onset sepsis patients, increased blood MALAT1 levels correlate with disease severity." (PMID 38473915, 2024). "In vivo, Malat1 inhibitor significantly increases the mortality in mice with late sepsis." (PMID 38385073, 2024). "In this study, we found that MALAT1 is upregulated in sepsis‐induced AKI models." (PMID 39390627, 2024). "Moreover, low Malat1 expression was detected in PMN-MDSCs isolated from the BM in late sepsis and in PBMCs isolated from septic patients." (PMID 38385073, 2024). "However, several reports have shown contradictory evidence, indicating a significant decrease in MALAT1 expression accompanied by an increase in hsa-miR-346 levels in patients with sepsis." (PMID 38473915, 2024). "Moreover, MALAT1 depletion restrained sepsis‐triggered ferroptosis in renal cells, as evidenced by decreasing Fe2+, MDA, and lipid ROS levels, along with increased cell viability and GSH levels." (PMID 39390627, 2024).